DPY19L1 (dpy-19 like C-mannosyltransferase 1)
Description:
C-mannosyltransferase that mediates the C-mannosylation tryptophan residues on target proteins. The reaction occurs on the luminal side of the endoplasmic reticulum and involves the transfer of a mannose unit from a dolichylphosphate mannose (Dol-P-Man) donor to an acceptor protein containing a WxxW consensus sequence (By similarity). C-mannosylates the first two tryptophans in the WxxWxxWxxC motif in thrombospondin (TSP) type-1 of UNC5A (By similarity). Regulates neurite extension during development (By similarity).
Synonyms: KIAA0877
Tractability: Antibody: UniProt predicts a signal peptide or a membrane-spanning region. PROTAC: ubiquitination databases record sites on it; its protein half-life has been measured.
Gene: Protein-coding gene on chromosome 7 (34,921,469 to 35,038,271, reverse strand). Ensembl gene ENSG00000173852.
Subcellular location: Endoplasmic reticulum membrane
Subcellular location (Human Protein Atlas): Vesicles
Gene Ontology:
Molecular function: mannosyltransferase activity
Cellular component: membrane; endoplasmic reticulum membrane
Genetic constraint (gnomAD): Loss-of-function variants: 15 observed, 36.48 expected, observed/expected ratio (o/e) 0.41, 90% interval 0.27 to 0.63. The upper end of that interval is the gene's LOEUF score, 0.63, which puts it in group 2 of 6, group 1 being the genes least tolerant of losing a copy. Missense variants: 254 observed, 342.79 expected, observed/expected ratio (o/e) 0.74, 90% interval 0.67 to 0.82. Synonymous variants: 96 observed, 113.24 expected, observed/expected ratio (o/e) 0.85, 90% interval 0.72 to 1.
Homologues: Orthologues: chimpanzee DPY19L1 (99% identical), dog DPY19L1 (96% identical), pig DPY19L1 (96% identical), mouse Dpy19l1 (90% identical), rat Dpy19l1 (90% identical), rabbit DPY19L1 (84% identical), guinea pig DPY19L1 (81% identical), macaque DPY19L1 (74% identical), tropical clawed frog dpy19l1 (61% identical), zebrafish dpy19l1l (61% identical), Caenorhabditis elegans dpy-19 (39% identical). Paralogues in human: DPY19L2 (61% identical), DPY19L3 (29% identical), DPY19L4 (24% identical).
Diseases named in the same sentence as DPY19L1 in open-access papers:
DPY19L1 is named in the same sentence as 5 diseases in open-access papers, as found by Europe PMC text mining. Sharing a sentence is not in itself a finding about the gene and the disease. The quoted sentences say what the papers report.
lung carcinoma (1 paper, 2020). "Therefore, to the best of our knowledge, this is the first report to reveal the association between DPY19L1 expression and the prognosis in lung cancer patients." (PMID 32235589, 2020). "However, as is the case for DPY19L1 and MARCH1, no publications have demonstrated the link between lung cancers." (PMID 32235589, 2020).
cancer (3 papers, 2018 to 2022). A tumor composed of atypical neoplastic, often pleomorphic cells that invade other tissues. "Bioinformatics analyses showed that the expression levels of six out of 25 genes (ERO1B, DPY19L1, NCAM1, RET, MARCH1, and SLC7A8) were associated with LUAD patient survival (p < 0.05), and pathway analyses indicated that major cancer signaling was altered in the subtypes." (PMID 32235589, 2020). "Increased expression levels of HLF, shown to promote cell-cycle progression in various cancers, ITGA2, MUC1, and DPY19L1 have also been proposed to confer prognostic value for the survival of patients suffering from LUAD malignancies." (PMID 36551790, 2022).
tumor (1 paper, 2026). "Furthermore, changes in the transcriptional expression of C-Man-Trp metabolism-related genes, C-mannosyltransferases (Dpy19l1 and Dpy19l3), and thrombospondin type I repeat superfamily genes (Thbs1, Spon1, and cellular communication network factor 1) were noted in tumor-associated cells and tissues." (PMID 41812877, 2026).
DPY19L1 also shares sentences with these, for which no sentence is quoted: cervical cancer (1 paper); Hyperglycemia (1).